CXCL9 (C-X-C motif chemokine ligand 9)
Diseases named in the same sentence as CXCL9 in open-access papers (continued):
Sharing a sentence is not in itself a finding about the gene and the disease.
tumor (continued). "CXCL9 was not produced by CD8+ T cells or cancer cells and it has not been investigated as part of the loop, but should be taken into consideration at the tumor site where it is largely produced by CD106+ DC." (PMID 39474427, 2024). "The results indicate that although CXCL9- and CXCL11-expressing SCCs exert anti-tumor activity, the CXCL10-expressing SCC failed to exert anti-tumor activity." (PMID 37218983, 2023). "The results demonstrated that although CXCL9- and CXCL11-expressing cells showed anti-tumor effects, CXCL10-expressing cells failed to exert anti-tumor effects." (PMID 37218983, 2023). "Although higher expression of VEGF was observed in tumor tissues transplanted with parental SCCVII cells, no significant suppression of VEGF expression was observed in CXCL9- and CXCL11-expressing tumor tissues (data not shown)." (PMID 37218983, 2023). "The results showed that CXCL9- and CXCL11-expressing cells markedly inhibited tumor growth, whereas CXCL10-expressing cells did not inhibit growth." (PMID 37218983, 2023). "CCL5 was found to be remarkably elevated in tumor tissues collected from PTC patients coexistent with HT than those without HT, and CXCL9, CXCL10, CXCL11, and CXCL13 were also reportedly upregulated in thyroid tissues from HT patients." (PMID 38137348, 2023). "CXCL9- and CXCL11-expressing cells showed significant anti-tumor activity, while CXCL10-expressing cells failed to exert an anti-tumor effect." (PMID 37218983, 2023). "We found that the secretion of CXCL9, CXCL10 and CXCL11 was significantly higher in central tumor tissues compared to nontumor tissues." (PMID 35954489, 2022). "In contrast to Brca2WT tumours, we did not observe a further increase in the number of CD3+ or CD8+ T cells upon Cxcl9 overexpression in the Brca2−/− model, possibly as a result of a saturation effect by the elevated STING-dependent chemokines, e.g. Cxcl10." (PMID 35314795, 2022). "CCL5 regulates the expression of CXCL9 (but not CXCL10) in the TAMs, thus allowing the recruitment of CD8 T cells within the tumor and tumor growth control." (PMID 36429101, 2022). "However, as circulating CXCL10 and CXCL9 levels did not correlate with tumor lymphocyte counts, their analysis from the blood samples cannot be used as a biomarker for T-cell rich tumors, further highlighting the importance of analyzing cytokines in primary tumor samples." (PMID 35927313, 2022). "The expression of CXCL9/10/11 and CXCR3 was negatively correlated with tumor purity, indicating that they were highly expressed in infiltrating immune cells rather than tumor cells in TME." (PMID 34321012, 2021). "Closer examination of the mechanism of action of GSK126 revealed its ability to promote the expression of IFN-γ driven chemokines CXCL9 and CXCL10 from the tumor cells, that work to traffic T cells without directly affecting T maturation and/or proliferation." (PMID 34336705, 2021). "Among the main reasons for this failure are the lack of classical T-attractive chemokines (e.g., CXCL9 and CXCL10), the dense tumor microenvironment matrix and the higher tumor-antigen heterogeneity, as compared to hematologic tumors." (PMID 34977027, 2021). "On the contrary, CXCL4, CXCL9, CXCL10, CXCL11, CXCL12, CXCL13, and CXCL14, lacking the ELR amino acid motif (ELR−), can inhibit tumor angiogenesis." (PMID 34497764, 2021). "Kaplan–Meier survival curves further showed positive correlations between CXCL9 expression level and OS (p = 0.048) and disease-free survival (DFS) (p = 0.032) in tumor tissues, but not with the other three chemokines in tumor or adjacent normal tissues." (PMID 34539647, 2021). "Immunohistochemistry staining showed abundant and uniform expression of CXCL5, CXCL9, and CXCL10 proteins in nontumor adjacent gastric tissues (N), but expression of these proteins was significantly downregulated in all tumor samples (C)." (PMID 33323542, 2020).
tumor (continued). "Although CXCL9 and CXCL10 are described as anti-angiogenic chemokines, their impact on the tumor vasculature under conditions of IL-27 treatment was not tested." (PMID 31637217, 2019). "Due to the absence of CD103+ DC-derived chemokines, such as CXCL9 and CXCL10, tumor infiltration by CTLs is prevented and antitumor immune responses are impaired." (PMID 31616443, 2019). "This occurred without implication of intratumoral chemokine expression because RNA‐seq analysis did not reveal reduced mRNA levels for CXCL‐9, CXCL‐10, and CXCL‐11 in bulk tumor tissue of male STAT1∆IEC mice (data not shown)." (PMID 29419930, 2018). "Additionally, they promote an increase in M1 macrophage population rather than M2 phenotype while upregulating production of CXCL9 and CXCl10 by these macrophages, thereby facilitating infiltration of CD8+ killer T cells into the tumor microenvironment." (PMID 39958358, 2025). "Remarkably, these two chemokines were also highlighted by a recent meta-analysis that evaluated existing biomarkers of ICB response, suggesting that CXCL9 and CXCL13 are indeed the strongest individual transcriptomic predictors of ICB response independent of tumor type." (PMID 38722600, 2024). "Further, 4-culture tumor spheroids decreased the concentrations of T-cell chemoattracting cytokines, i.e., CCL4, CCL5, and CXCL9, when compared with the non-cancerous spheroids, revealing a critical immunosuppressive feature of the different types of cells forming the tumor spheroids." (PMID 37519820, 2023). "Differential gene expression showed an enrichment of genes involved in T cell recruitment (CXCL9, CXLC10) and interferon-gamma activity (GBP1, STAT1) in the macrophage compartment of responding tumours, while non-responders were enriched in immunosuppressive markers (GPNMB, CCL18)." (PMID 38030622, 2023). "In stromal-rich regions that lacked CK + tumor cells, 1045 T cells + CD40 agonist increased Cxcl9/Cxcl10 expression by macrophage and 1045 T cells appeared to colocalize with the Cxcl9 + macrophage in these stromal regions, similar to our results in resected human PDA." (PMID 36472588, 2023). "However, no marked infiltration of NK1.1-positive cells was observed in CXCL9- and CXCL11-expressing tumor tissues (data not shown)." (PMID 37218983, 2023). "Since CXCL9 and CXCL10 are IFN-γ–inducible chemokines, lack of IFN-γ secretion by immune cells in the tumor could lead to a negative feedback loop, preventing further CD8 T cell recruitment." (PMID 35103755, 2022). "On the basis of the principle of ceRNA hypothesis, C22orf34, RFPL1S, and LINC00996 shared same expression patterns as CXCL10, CXCL9, CCL5, FCGR3A, and CCR2, all which were upregulated in tumor tissues of PTC with HT compared with those without HT." (PMID 36266640, 2022). "These complicated and contradictory roles of CXCL9 on tumor growth may be related to the intricate spatial and temporal interaction of immune responses in the TME, not simply the location where CXCL9 is secreted." (PMID 36362062, 2022). "In contrast, CCL5, CXCL9, and CCL10 were upregulated in the low-risk group; high expression levels of CXCL9 and CXCL10 were correlated with improved OS in most tumors, and anti-PD1 therapy was not beneficial in CXCR3−/− (receptor of CXCL9 and CXCL10) tumor-bearing mice." (PMID 35795712, 2022). "Therefore, CXCL9, CXCL10, and CXCL11 have crucial, nonredundant, cell-autonomous roles mediating immune cell infiltration into tumors, and inducing effective anti-tumor immunity." (PMID 35493527, 2022). "The quantitative PCR results were consistent with the transcriptome results, showing that the expression of CCL2, CCL3, CCL5, and CXCL9, but not CCL17 or CCL22, was markedly higher in 1.5 mg/kg AAGL-treated tumor-bearing mouse livers than in those of control mice." (PMID 33710817, 2021).
tumor (continued). "Circulating CXCL9 is a predictor of poor prognosis in HNSCC;51 however, in the context of CXCR3 expression in bintrafusp alfa responder tumors, it has the potential to induce antitumor immunity rather than promote tumor expansion." (PMID 34433873, 2021). "Relative to tumor sections stained with a negative control probe, dapB, or a normal adjacent lung stained with a probe for murine Cxcl9 (another negative control), four separate LLC-NT or LLC-sh21 tumors stained positive for Cxcl9." (PMID 31133614, 2019). "As a result, TILs highly expressing CXCR3, which is the receptor for CXCL9 and CXCL10, could not be recruited to the tumor site." (PMID 30064449, 2018). "It was later found that in a tumor model resembling non-T cell-inflamed human tumors, adoptive transferred T cells failed to traffic into tumor site due to the absence of CD103+ DC secreting CXCL9 and CXCL10." (PMID 30064449, 2018). "Accordingly, we analyse the cytokine expression changes (more than 1.5 log2, 2.8 fold, p < 0.05, t-test) between No take and Take tumours and found a large series of chemokine/cytokine overexpressed in the No take samples, among them IFNG, CXCL13, CXCl9, CXCl11, CXCL10 and CCL5." (PMID 28588211, 2017). "Furthermore, in keeping with the effect of EZH2 inhibition in tumor cells, Mo-TAMs from EPZ-6438-treated MCS showed a consistent enhanced expression of monocyte chemoattractants CCL2 and VEGF but not Th1-recruiting chemokines (CXCL9, CXCL10, CXCL11)." (PMID 33922336, 2021). "Despite the higher CXCL9 levels in COX-2MECKO tumors, however, theabsolute number of CD3+ cells by flow cytometry was not higher than in WTtumors suggesting a local influence of tumor cell COX-2 derived mediators in limitingimmune cell function rather than a simple recruitment effect." (PMID 24004819, 2013).
infection (370 papers, 2005 to 2026). The state of being infected such as from the introduction of a foreign agent such as serum, vaccine, antigenic substance or organism. "During acute inflammation caused by PCN033 infection, Cxcl9, Cxcl10 and Cxcl11 induction recruits immune cells for PCN033 clearance." (PMID 41295668, 2025). "CXCL9 is upregulated during infection with pathogenic Leptospira and binds to the CXCR3 receptor, which is expressed at all stages of CD4 T-cell development." (PMID 39534703, 2024). "Other transcripts encoding pro-inflammatory genes identified as up-regulated in response to sublethal PVM infection and down-regulated in response to L. plantarum include those encoding Ccl2, Ccl8, Cxcl9, Cxcl10, and resistin-like molecule alpha (Retnla)." (PMID 34959580, 2021). "All three infection types were associated with elevated BALF CXCL9 concentrations compared to healthy biopsies." (PMID 31414076, 2018). "Previous work by our laboratory found that depletion of IFNγ-producing NK1.1+ CD3- cells reduced CXCL9 levels in the C. rodentium-infected gut, leading to increased host susceptibility to infection." (PMID 25643352, 2015). "Later during infection, the lungs of Fas- and FasL-deficient mice expressed significantly more CXCL9, which can reflect increased migration of alveolar macrophages and inflammatory monocytes." (PMID 25873756, 2015). "Neutralization of this CXCL9-dependent antimicrobial activity increased host susceptibility to infection, leading to bacterial penetration into intestinal crypts and increased tissue pathology." (PMID 25643352, 2015). "The Fas and FasL- deficient mice showed significantly less CXCL9 production in the vaginal lavages at 3 and 7 day of infection in comparison to HSV-2 infected wild-type strain (p≤0.01)." (PMID 23922974, 2013). "CXCL9 alone could cause differences in the recruitment of T cells to the site of infection." (PMID 39641542, 2025). "From an immunological perspective, proteomics studies found that pulmonary dysfunction in LC at 4 months post‐infection was associated with upregulated pathways of chemotaxis of phagocytes, leukocyte activation, and cardiac dysfunction, and with elevated levels of chemokine CXCL9 during AC." (PMID 40084919, 2025). "Notably, infection by the Delta variant induced significantly higher levels of chemokine mRNAs such as CXCL9, CXCL10, CXCL11, and CCL2 than infection by the wild type and there was negligeable upregulation of cytokine and chemokine mRNA levels in mice infected with Omicron at 3 dpi." (PMID 38257760, 2023). "As early as wk 3 post infection we were able to observe distinct transcriptional profiles in infected mice compared to naïve controls including increased expression of chemokines (Cxcl9 and Cxcl10) and genes associated with MHCII expression (H2-Aa, H2-Ab1 and H2-Eb1)." (PMID 35958580, 2022). "Given our results following infection of CXCL9-depleted mice, we hypothesized that IFNγ-/- mice would be similarly susceptible to crypt penetration by C. rodentium due to the attendant decrease in CXCL9 expression." (PMID 25643352, 2015). "(Subjects with inflammatory complications had increased CXCL9 as compared to those with the infection only phenotype, P = 0.01)." (PMID 41608052, 2026). "CXCL9 orchestrates immune cell recruitment and activation at infection sites, supporting trained immunity by establishing a pro-inflammatory environment conducive to pathogen clearance." (PMID 39819562, 2025). "When examining individual cytokines, the chemokines IP10, CXCL11, and CXCL9 (involved in the recruitment and maturation of the immune response) were upregulated after infection with all strains of SARS-CoV-2 except Delta." (PMID 41157615, 2025). "The majority of post‐COVID‐19 proteome studies show a similar trend of lower concentrations of CXCL10 and CXCL9 after infection, even in long‐COVID‐19 patients." (PMID 40949320, 2025).
infection (continued). "Increased Cxcl9 and Cxcl10 are in line with observations during infection and vaccination where IFN-I signaling is suppressed and chemokine transcription remained elevated." (PMID 40062995, 2025). "A major contributor to iAge was chemokine CXCL9 secreted by immune cells to attract them to the site of infection." (PMID 40908179, 2025). "Like PMs, THP-1 cells also produced IL-6, CCL4, CCL2, IL-1RA, CCL3, and CXCL9 upon infection with the RSV strain A-0594, although the peak of these responses differed in some cases." (PMID 41280933, 2025). "The expression of CXCL9 remained unchanged upon infection, and only the inhibition of INOS with AMG resulted in a significant down-regulation of mRNA (p = 0.022)." (PMID 41156686, 2025). "The protein expression of three proteins (IL-8, CXCL9, and CXCL10) were significantly increased in caspase-4-deficient cells compared to Cas9 cells following HK1651 infection." (PMID 40137780, 2025). "Our studies revealed an increase in TLR3 expression and phosphorylation of NF-κB following RRV and Ro1845VP4-G446R infection, as well as an increase in the cytokines CXCL9 and CXCL10." (PMID 38860860, 2024). "With respect to the female response to infection-induced neuroinflammation, there was significant upregulation in the expression of CXCL9, CXCL10, BDNF, IL-13 and KCNN4 in the medulla oblongata." (PMID 38879567, 2024). "Spinal cords of wild-type mice contained significantly higher levels of IFN-β and IL-6 at day 5 post-infection (p ≤ 0.05) and IFN-γ, IL-1β, CCL3, CCL5, and CXCL9 at 5 and 9 days post-infection (p ≤ 0.05)." (PMID 39339840, 2024). "Specifically, CXCL10 is primarily expressed on glia and recruits lymphocytes and phagocytes to inflamed areas to limit the spread of infection and as is the case with CXCL9, aids in T-cells responses to bacterial infection." (PMID 38879567, 2024). "As effector cells, NK cells are recruited to the site of infection by chemokines secreted by macrophages, such as CXCL9 and CXCL10, which are produced in response to infection." (PMID 39770782, 2024). "At 48 hours after infection, significant reductions in the mRNA expression levels of Cxcl9 and Cxcl10 were detected in the FP skin of CD1d-KO mice compared with WT mice." (PMID 39088280, 2024). "On the other hand, other chemokines involved in T cell trafficking such as Cxcl9 and Cxcl10 are highly expressed during the first few days of infection, as is their receptor Cxcr3." (PMID 38352492, 2024). "CXCL9 was also identified as upregulated in the intestine tissue of sheep after four hours of infection by Echinococcus granulosus eggs." (PMID 38397178, 2024). "By 24 hours after infection, we also detected increased expression of genes involved in a broader inflammatory response, including Ccl2, Cxcl9, Cxcl10, and Ccl7, which were upregulated across the major LNSC subsets." (PMID 38194268, 2024). "Recent studies have shown that Ly6Chi monocytes surround S. Typhimurium-confining granulomas in the spleen and recruit CD4+ T cells to the foci of infection by producing CXCL9 and CXCL10, both are ligands for CXCR3 expressed by Th1 cells." (PMID 37733817, 2023). "We can conclude that the in vitro pre-stimulus of cells with itaconic acid prior to infection with L. infantum increases the parasite load due to the overexpression of inflammatory markers such as Il6 and Cxcl9." (PMID 37235312, 2023). "Upon vaccination with the LAV, IMs expressed T cell chemoattractant CXCL9 that attracted CD4+ T cells to the foci of infection, where IMs also served as a potent source of antigen presentation and Th1-promoting cytokine IL-12." (PMID 37733817, 2023). "At day 1 after infection, the cytokine expression (IL-6, CXCL-9, IP10, and IFN-ß) in lung samples of MA60-treated, influenza virus-infected mice was stronger than in all other experimental groups." (PMID 38143489, 2023). "In patients with infection confirmed at T3, both CXCL-9 and CXCL-10 levels were higher from T0 to T4." (PMID 37755950, 2023).